ATF2 (activating transcription factor 2)
Diseases named in the same sentence as ATF2 in open-access papers (continued):
Sharing a sentence is not in itself a finding about the gene and the disease.
lung carcinoma (14 papers, 2011 to 2023). "Transcription factors (NFATc, ATF2, and c-Jun) upregulated in lung cancer aggressive cells, increasing angiopoietin-like protein 2 (ANGPTL2) expression, and cell motility and invasion." (PMID 36476606, 2022). "The results of qRT-PCR and WB assay showed that the expressions of Wnt5a and other proteins in the ATF-2 knockdown lung cancer cells (represented by si-ATF-2) were lower than those in the normal lung cancer cells." (PMID 35692887, 2022). "Then, the expression of Wnt/Ca2+ pathway proteins was further detected in ATF-2 knockdown lung cancer cells." (PMID 35692887, 2022). "The expression of ATF-2 in lung cancer cells was further detected by IHC, and the results showed that the expression of ATF-2 in NSCLC tissues was significantly higher than that in adjacent normal tissues and mainly concentrated in the nucleus." (PMID 35692887, 2022). "To investigate the effect of ATF-2 expression on Wnt/Ca2+ signaling pathway activity, we used CRISPR/Cas9 technology to knock out the ATF-2 gene in lung cancer cells." (PMID 35692887, 2022). "The expression of NFE2L2 is also regulated by ubiquitin specific peptidase 11 (USP11) and activating transcription factor 2 (ATF2) in lung cancer cells." (PMID 34742351, 2021). "Concordantly, the targeting relation between ATF2 and miR‐26b has been validated in γ‐irradiated lung cancer cells." (PMID 32476275, 2020). "Further analysis of the expression of ATF2 mRNA in clinical samples revealed that the level of ATF2 mRNA was lower in normal lung tissues than in lung cancer tissues and that ATF2 expression was inversely correlated with the miR-144-5p levels." (PMID 29850528, 2018). "Subsequent analysis verified that miR-144-5p expression was negatively related to ATF2 abundance in lung cancer and normal lung tissues." (PMID 29850528, 2018). "We need further study regarding the transcriptional control of miR-26b by ATF2 in lung cancer cells; however, JNK activity and expression of ATF2 repressed expression of miR-26b is performed in the current study." (PMID 21901137, 2011). "The effects of SP600125 on the expression of ATF2 mRNA and miR-26b were also confirmed in A549 lung cancer cell line." (PMID 21901137, 2011). "The results showed that both ATF-2 and Wnt/Ca2+ signaling pathways were abnormally expressed in lung cancer cells, which may be related to the development of lung cancer." (PMID 35692887, 2022). "After ATF-2 knockdown, Wnt/Ca2+ signaling pathway activity was decreased in lung cancer cells." (PMID 35692887, 2022). "Given that NEAT1 was involved in lung cancer tumorigenesis and metastasis, we next investigated whether ATF2 exerted its oncogenic role through upregulating NEAT1." (PMID 33298086, 2020). "In addition, curcumin has been found to reduce MMP-9 protein level in A549 cells by downregulating PKCα, NOX-2, and ATF2 expression, and inhibiting ROS intracellular production in lung cancer A549 cells." (PMID 31817718, 2019). "Interestingly, we recently found that the human ANGPTL2 minimal promoter (−168 to +98) also contains a putative CRE site essential for ANGPTL2 expression and that ATF2 binds to this site in human lung cancer cells." (PMID 23469106, 2013). "From these results, we concluded that IR-induced up-regulation of ATF2 was coordinately enhanced by suppression of miR-26b in lung cancer cells, which may enhance the effect of IR in the MAPK signaling pathway." (PMID 21901137, 2011). "Therefore, it is speculated that the expression of ATF-2 can promote the proliferation and development of lung cancer cells." (PMID 35692887, 2022). "This study demonstrated that inhibition of PKCα/NOX-2/ROS/ATF2 signaling pathway decreases expression of MMP-9, suggesting one of the mechanisms of anti-invasive effect by curcumin in lung cancer cells." (PMID 31817718, 2019). "The other genes AR, ATF2, CUL1, EP300, GATA4, LEF1, SKP2 in these subnetworks have also been identified as important in lung cancer." (PMID 24369052, 2013).
lung carcinoma (continued). "Studies have shown that there is a negative correlation between expression of ATF-2 and survival time of lung cancer patients; that is, patients with high expression of ATF-2 have a short survival time, while patients with low expression of ATF-2 have a long survival time." (PMID 35692887, 2022). "From these results, we could demonstrate that exposure of H1299 lung cancer cells to IR induced MAPK signaling followed by suppression of miR-26b expression, which led to the escape of ATF2 mRNA from posttranslational suppression by miR-26b." (PMID 21901137, 2011).
viral infection (12 papers, 2008 to 2025). "Virus infection results in the coordinate activation of NF-κB, ATF-2/c-Jun, IRF3, and IRF7 that assemble sequentially on this IFN-β enhancer region." (PMID 24722640, 2014). "In both, ATF2 expression was inhibited by viral infection with the corresponding mouse or human shRNA (shATF2)." (PMID 21203491, 2010). "ATF2 plays an important role in the skeletal system, central nervous system, and inflammation and is involved in oncogenic transformation, adaptive responses of the cell to viral infections, and toxic stresses." (PMID 29577053, 2018). "A main function of JNK and p38 in the host defense against virus infection is to regulate the activation of AP-1 (ATF-2/c-Jun) that participates in the enhanceosome structure controlling IFNβ expression and contributes to the regulation of proinflammatory cytokine expression." (PMID 29234123, 2017). "The IFN-β promoter has been extensively studied, and a role for an enhanceosome consisting of IRF3, AP-1 (composed of ATF2 and c-jun), and NF-κB has been established in IFN-β expression in response to viral infection." (PMID 27795299, 2017). "STAG2, an enhancer of TNF production, and the member of the MAPK pathway, ATF2, a transcription activator of both IFN-β and TNF-α in response to virus infection, were downregulated." (PMID 18796724, 2008). "It was first reported that human IFN-β gene expression after virus infection requires the assembly of an enhanceosome, which includes four groups of transcription factors, the high mobility group protein HMGI, ATF2/c-JUN, NF-κB, and interferon response factors (IRFs), respectively." (PMID 41427291, 2025).
hepatocellular carcinoma (11 papers, 2010 to 2025). A malignant tumor that arises from hepatocytes. "In the regulation of transcription factors, STAT6 essentially regulates two functional disorder modules, while TF such as AR and ATF2 has a driving effect on one module, which affects the occurrence and development of hepatocellular carcinoma." (PMID 34651050, 2021). "In hepatocellular carcinoma, GAS5 has been found to enhance radiosensitivity via sponging miR-144-5p, which subsequently upregulates the expression of ATF2." (PMID 39958058, 2025). "Using transient transfection and chromatin immunoprecipitation approaches in hepatoma cells, we report the characterization of a functional Amino Acid Response Element (AARE) in the TRB3 promoter and the binding of ATF4, ATF2 and C/EBPβ to this AARE sequence." (PMID 21203563, 2010). "Using transient transfection and chromatin immunoprecipitation approaches in hepatoma cells, we report the characterization of an Amino Acid Response Element (AARE) in the TRB3 promoter and the binding of ATF4, ATF2 and C/EBPβ to this AARE sequence." (PMID 21203563, 2010). "It has been reported that the antitumorigenic effects of RSV are mediated by the upregulating of the cyclic AMP response element (CRE)-binding proteins (CREB)- and activating transcription factor 2 (ATF2)-controlled target genes when HEK293 cells and HepG2 hepatoma cells treated with RSV at 20 μM." (PMID 31310624, 2019).
non-small cell lung carcinoma (11 papers, 2016 to 2024). A group of at least three distinct histological types of lung cancer, including non-small cell squamous cell carcinoma, adenocarcinoma, and large cell carcinoma. "Additionally, ATF2 is implicated in platinum resistance in non-small cell lung cancer treatment and is targeted to restore chemotherapy sensitivity to platinum." (PMID 39633985, 2024). "For example, miR-144-5p acts as a tumour suppressor gene and enhances the radiosensitivity of non-small cell lung cancer cells by targeting ATF2." (PMID 39103836, 2024). "The expression of ATF-2 in normal bronchial epithelial cells, non-small-cell lung cancer tissues, and paracancerous normal tissues was detected by qRT-PCR." (PMID 35692887, 2022). "The expression of ATF-2 and pathway-related genes in non-small-cell lung cancer was detected by qRT-PCR and Western blotting." (PMID 35692887, 2022). "ATF2 is overexpressed in non-small cell lung cancer cells, and studies have shown that ATF2 increases the resistance of non-small cell lung cancer to cisplatin and radiotherapy by repairing DNA." (PMID 32014006, 2020). "In the present work, ATF2 was selected as a potential target of microRNA-299-5p based on gene prediction to study the regulation of ATF2 expression by microRNA-299-5p in non-small cell lung cancer cells." (PMID 32014006, 2020). "The results showed that overexpression of ATF2 blocked the growth of non-small cell lung cancer cells by microRNA-299-5p, which demonstrated that ATF2 participates in the regulation of growth of non-small cell lung cancer cells by microRNA-299-5p." (PMID 32014006, 2020). "MiR-299-5p binds to the 3′-UTR of the ATF2 mRNA and prevents gene expression, thereby inhibiting the proliferation and metastasis of non-small cell lung cancer cells." (PMID 32014006, 2020). "This indirectly proves that ATF2 is an important downstream target for microRNA-299-5p through which the biological characteristics of non-small cell lung cancer are altered." (PMID 32014006, 2020). "ATF-2 is overexpressed in non-small-cell lung cancer tissues." (PMID 35692887, 2022). "We constructed A549 cells overexpressing ATF2 in order to determine whether ATF2 is involved in the proliferation of non-small cell lung cancer cells induced by microRNA-299-5p." (PMID 32014006, 2020). "The results showed that overexpression of ATF2 could block the effect of microRNA-299-5p on the metastasis of non-small cell lung cancer cells, which demonstrated that ATF2 may be involved in the regulation of microRNA-299-5p on the metastasis of non-small cell lung cancer cells." (PMID 32014006, 2020). "GPF regulates miR-299-5p/ATF2 axis in A549 cells via the AMPK signalling pathway, thereby inhibiting the proliferation and metastasis of non-small cell lung cancer cells." (PMID 32014006, 2020). "Additionally, via the c-Met/BVR/ATF-2 pathway, lncRNA NR2F2-AS1 activates the EMT process and fosters the development of non-small cell lung cancer." (PMID 39633985, 2024). "ATF-2 activated the Wnt/Ca2+ pathway and promoted the expression of Wnt5a, Wnt11, CaMKII and NLK, which regulated the proliferation and invasion of non-small cell lung cancer cells, suggesting that Ca signaling is directly involved in malignant behavior of tumor cells." (PMID 39687904, 2024).
esophageal cancer (10 papers, 2013 to 2025). A primary or metastatic malignant neoplasm involving the esophagus. "Thus, a combined treatment of oxidative stress with the knockdown of ATF2 caused better apoptotic effects in oesophageal cancer cells." (PMID 23800081, 2013). "In esophageal carcinoma, exosomes derived from M2 macrophages can carry high levels of LncRNA AFAP1-AS1 into esophageal carcinoma cells to sponge miR-26a and promote the expression of ATF2, facilitating the migration, invasion, and lung metastasis of EC cells." (PMID 40612677, 2025). "The results showed that ATF2 is highly expressed in the tumor tissues of diffuse large B-cell lymphoma, esophageal carcinoma, pancreatic adenocarcinoma, stomach adenocarcinoma, and thymoma compared to normal tissues." (PMID 39633985, 2024). "M2-Exos transfer LncRNA AFAP1-AS1, down-regulate miR-26a and up-regulate activating transcription factor 2 (ATF2), thus promoting esophageal cancer invasion and metastasis." (PMID 34368234, 2021). "For example, lncRNA AFAP1-AS1 urged metastasis of esophageal cancer cells by binding to miR-26a and then augmenting ATF2 expression." (PMID 34289449, 2021). "Targeting M2 macrophages and the lncRNA AFAP1AS1/miR-26a/ATF2 signaling axis is a potential therapeutic strategy for esophageal cancer." (PMID 34368234, 2021). "M2-Exos carry lncRNA AFAP1-AS1, downregulating miR-26a and upregulating activating transcription factor 2 (ATF2), hence facilitating esophageal cancer (EC) penetration and metastasis." (PMID 41357196, 2025). "In esophageal cancer (EC), M2 macrophage-derived sEV consist of high levels of lncRNA AFAP1-AS1 and activating transcription factor 2 (ATF2) but a decreased level of miR-26a." (PMID 36263199, 2022). "Actin filament associated protein 1 antisense RNA1 (LncRNA AFAP1-AS1) delivered by M2-sEVs can downregulate miRNA-26a and upregulate activating transcription factor 2 (ATF2) to affect the migration and metastasis of esophageal cancer cells, as well as in vitro lung tumor metastasis in EC." (PMID 35832790, 2022). "Only two transcription factors, ATF2 and CCAAT/enhancer-binding protein beta (CEBPB), have not yet been described in oesophageal cancer." (PMID 23800081, 2013).
gastric cancer (10 papers, 2016 to 2026). A primary or metastatic malignant neoplasm involving the stomach. "We found that high expression of RP11-357H14.17 in stomach cancer tissues were associated with ATF2-related gene sets including “ATF2_s_UP v1_up,” “ATF2_up." (PMID 34195276, 2021). "Sorafenib induces ferroptosis, and its effect on ferroptosis in gastric cancer cells strongly correlates with ATF2 expression." (PMID 40959280, 2025). "The protein expression and location of ATF2 in gastric cancer tissues was detected with immunohistochemistry assay, and the clinical significance was analyzed using TCGA and GEO database." (PMID 35641966, 2022). "We earlier demonstrated that H. pylori can upregulate COX-2 via the p38 mitogen-activated protein kinase (MAPK)/activating transcription factor-2 (ATF-2) signaling pathway in MKN45 gastric cancer cells." (PMID 27198692, 2016). "In addition, PAK1 has been reported to regulate the alternative splicing of CD44 by phosphorylating PCBP115 or promote the expression of CD44 through the PAK1/ATF2/miR-132 cascade in gastric cancer." (PMID 41459112, 2026). "Furthermore, ATF2 upregulation in gastric cancer correlates with a worse clinical prognosis, and silencing ATF2 suppresses the malignant phenotype of gastric cancer cells." (PMID 39633985, 2024). "Recent studies show that miR-622 is associated with tumor metastatic capability in gastric cancers and can suppress glioma invasion and migration by directly targeting activating transcription factor ATF2, but no data have been released about a miR-622 neuromodulation activity." (PMID 27611585, 2016). "ATF2, a member of the ATF/CEBP family, has been confirmed to be involved in regulating the biological behaviors of gastric cancer cells." (PMID 40959280, 2025). "For example, ATF2 inhibits sorafenib-induced ferroptosis in gastric cancer by stabilizing SLC7A11 through HSPH1, suggesting that targeting ATF2 could enhance sensitivity to sorafenib." (PMID 40946428, 2025). "Similarly, results in ATF2 stable cell lines also showed that cisplatin treatment promoted the activation of ATF2 in MGC-803 and HGC-27 gastric cancer cells, while in AGS cells p-ATF2 changed little." (PMID 35641966, 2022).
pancreatic cancer (9 papers, 2011 to 2024). "For example, in pancreatic cancer, phosphorylated-ATF-2 protein expression is upregulated, promoting pancreatic cancer cell invasion and epithelial cell mesenchymal transformation." (PMID 35692887, 2022). "ATF2 was reported to promote metastasis by regulating EMT in solid tumors such as pancreatic cancer." (PMID 27377902, 2016). "When RNA from pancreatic tumors was used, antisense intronic transcription was detected in three additional loci (ATF2, TGFBR2 and MAP3K1), which produced both sense and antisense messages." (PMID 22078386, 2011).
Parkinson’s (8 papers, 2014 to 2025). "In Alzheimer’s and Parkinson’s disease, ATF2 expression is downregulated in the hippocampus and caudate nucleus, indicating that ATF2 is essential for neuronal viability and normal neurological functions." (PMID 37973625, 2024). "In neurodegenerative diseases like Alzheimer’s, Parkinson’s, and Huntington’s diseases, ATF2 is downregulated in the hippocampus and the caudate nucleus." (PMID 32993798, 2020). "ATF2 is downregulated in the hippocampus and the caudate nucleus in Alzheimer’s, Parkinson’s, and Huntington’s diseases." (PMID 32993798, 2020). "Also, Atf2, an abundant TF in normal brains, was significantly down-regulated in the brains with Alzheimer’s, Parkinson’s, and Huntington’s diseases, consistent with our findings." (PMID 31959236, 2020). "Although ATF2 is generally localized to the nucleus where it functions as a transcription factor, it has been detected in the cytoplasm of degenerating neurons of patients with Alzheimer’s, Parkinson’s and Huntington’s diseases." (PMID 30497386, 2018). "In Alzheimer's, Parkinson's, and Huntington's diseases, ATF2 is downregulated in the hippocampus and caudate nucleus, implying that ATF2 may be essential for neuronal viability and normal neurological function." (PMID 25049453, 2014).
leukemia (7 papers, 2009 to 2026). A malignant (clonal) hematologic disorder, involving hematopoietic stem cells and characterized by the presence of primitive or atypical myeloid or lymphoid cells in the bone marrow and the blood. "ATF2 acts as a downstream agent to MAP2K7 alongside c-jun, which increases susceptibility to leukemia." (PMID 37955015, 2023). "However, ATF2 is also involved in the tumorigenesis of several other cancers, including skin cancers, leukemia, renal cell carcinoma, brain tumors, and cervical cancer." (PMID 37955015, 2023). "It is a member of the activating transcription factor 2 cAMP-binding protein family and is activated by a variety of kinases including protein kinase A and is involved in tumorigenesis of endocrine tissues and different forms of leukemia." (PMID 19689798, 2009). "For both dimers of type ATF2; HMG-B the predicted cell types are leukemia (K562), prostate (normal cell, PrEC), and epithelium (SAEC, RPTEC, HMEC, and HEEpiC)." (PMID 26847699, 2016).